FTO (FTO alpha-ketoglutarate dependent dioxygenase)
Diseases named in the same sentence as FTO in open-access papers (continued):
Sharing a sentence is not in itself a finding about the gene and the disease.
depression (continued). "Contrarily, downregulation of simulated FTO induced anxiety- and depression-like behaviors in mice." (PMID 35634463, 2022). "Similarly, FTO was demonstrated to target the CaMKII/CREB signaling pathway to regulate hippocampal synaptic plasticity, and activation of FTO in the hippocampus alleviated chronic restraint stress-induced depression-like behaviors in mice." (PMID 36118889, 2022). "The findings of this study suggest that FTO may lead to depression by downregulating the level of dopamine." (PMID 35528183, 2022). "In addition, chronic restraint stress can downregulate the expression of FTO in mouse hippocampus, and thus induce anxiety- and depression-like behaviors in mice." (PMID 35634463, 2022). "For instance, depression had shown to increase the effect of the FTO gene on BMI." (PMID 35918662, 2022). "Studies have shown that FTO is a demethylase that regulates the level of m6A in mRNA and might play key roles in the occurrence and development of addiction, depression, schizophrenia, and other diseases." (PMID 35528183, 2022). "It would be interesting to further investigate the differential mechanisms of anxious versus nonanxious depression by comparing common depression models and the hippocampal FTO deficiency model." (PMID 34836959, 2021). "In our study, the MC4R variant rs571312(and others, but not FTO) was identified as an influential (and potentiallyinvalid) instrument in major depressive disorder analysis, but not in the remainingoutcomes." (PMID 27601421, 2016). "Notably, overexpression of FTO can reverse these structural and behavioral changes, and antidepressant treatment with fluoxetine has been shown to upregulate hippocampal FTO expression, further demonstrating the role of m6A in depression." (PMID 40590504, 2025). "However, whether FTO in ACC is involved in the occurrence or maintenance of anxiety- and depression-like behaviors caused by NP remains unclear." (PMID 35634463, 2022). "FTO may be an endogenous trigger of NP-induced anxiety- and depression-like behaviors, which will improve our understanding of mechanism of anxiety- and depression-like behaviors induced by NP, and may provide potential targets for developing new therapeutic strategies." (PMID 35634463, 2022). "Therefore, we further examined whether ADRB2 contributed to FTO-mediated depression-like behaviors in the hippocampus." (PMID 34836959, 2021). "While most of the existing depression models are comorbid with anxiety, our model of FTO deficiency in the hippocampus may serve as a model of nonanxious MDD." (PMID 34836959, 2021). "Therefore, the effect of depression status on BMI-increasing alleles is not restricted to the FTO gene, but is observed across the spectrum of polygenic variation associated with BMI." (PMID 26125155, 2015). "It’s reported that the downregulation of FTO in the anterior cingulate cortex (ACC) by modulating matrix metalloproteinase-9 (MMP-9) mRNA methylation participates in anxiety- and depression-like behaviors in neuropathic pain." (PMID 38384936, 2024). "Contrarily, FTO knockdown in ACC of naïve mice can induce anxiety- and depression-like behaviors in mice." (PMID 35634463, 2022). "The study sought to indicate that FTO regulates the participation of MMP-9 in the generation and maintenance of anxiety and depression-like behaviors under NP conditions." (PMID 35634463, 2022). "In addition, the potential roles of FTO gene in drug addiction, major depression (MDD), and schizophrenia (SCZ) through regulating m6A modification of dopamine related genes were also highlighted." (PMID 35528183, 2022). "In conclusion, downregulation of FTO in ACC by regulating MMP-9 mRNA methylation level contributes to the occurrence of anxiety- and depression-like behaviors in NP mice." (PMID 35634463, 2022). "Although these studies suggested that FTO could play a vital role in MDD, the mechanism behind specific induction of depression-like behaviors has yet to be clarified." (PMID 34836959, 2021).
depression (continued). "The expression of hippocampal FTO is decreased in patients with MDD and three mouse models of depression." (PMID 34836959, 2021). "According to our findings, the expression of hippocampal FTO was decreased in both patients with MDD and the three mouse models of depression." (PMID 34836959, 2021). "However, the role of FTO in the pathophysiology of depression remains largely unknown." (PMID 34836959, 2021). "However, another study on the interactions between FTO gene polymorphism, depression and serum vitamin D level reported that A‐allele of FTO rs9939609 polymorphism might be associated with depression independent of serum vitamin D level." (PMID 34490746, 2021). "In one study, global m6A methylation is decreased in the whole blood of both human and mice after acute stress, and in another study, ALKBH5 and FTO as m6A demethylases and METTL3, METTL14, and WTAP as m6A methyltransferases are altered in the MDD patients and the depression models." (PMID 38773146, 2024). "We further explored whether FTO downregulation in ACC regulates anxiety- and depression-like behaviors through MMP-9/BDNF axis coordination in NP model." (PMID 35634463, 2022). "This article reviews the role of FTO in the development of addiction, depression, and SCZ and discusses the mechanism by which FTO may influence the occurrence and development of these neurological diseases." (PMID 35528183, 2022). "Thereafter, we explored whether FTO knockdown in ACC could induce anxiety- and depression-like behaviors." (PMID 35634463, 2022). "Importantly, FTO+/- mice are less sensitive to stress stimulation, and FTO knockout mice show decreased anxiety and depressive behaviors, suggesting that deletion of FTO may affect brain functions by affecting the intestinal flora and then lead to the occurrence of depression." (PMID 35528183, 2022). "Blocking the downregulation of FTO in the ACC induced by peripheral nerve injury could reverse the anxiety- and depression-like behaviors of mice." (PMID 35634463, 2022). "Knockdown of FTO in ACC of control mice can simulate the increase in proBDNF protein level and the decrease in mBDNF protein expression in ACC of CCI mice, and can induce anxiety- and depression-like behaviors in mice." (PMID 35634463, 2022). "Our study demonstrated that FTO in the hippocampus specifically mediated depression-like behaviors without affecting anxiety-like behaviors." (PMID 34836959, 2021). "RNA methyltransferases (METTL3, METTL14, and WTAP) and demethylases (FTO and ALKBH5) are altered in the MDD patients and the mouse models of depression." (PMID 38773146, 2024). "Therefore, we hypothesized that downregulated FTO in ACC contributes to anxiety- and depression-like behaviors-induced by NP by increasing m6A level of MMP-9 mRNA." (PMID 35634463, 2022). "Combined with our experimental results, the FTO in ACC of NP mice reduces the protein expression of MMP-9 by affecting the translation efficiency of MMP-9 mRNA, thus hindering the transformation from proBDNF to mBDNF and resulting in anxiety- and depression-like behaviors in mice." (PMID 35634463, 2022). "Interestingly, downregulation of hippocampal FTO did not affect anxiety-like behaviors that are often observed in stress-induced models of depression, including those employed in the current study." (PMID 34836959, 2021).
pancreatic cancer (52 papers, 2013 to 2025). "In the previous experiment, we demonstrated that FTO knockdown can cause G2 phase arrest in pancreatic cancer cells, thereby affecting cell proliferation and regulating their drug resistance." (PMID 37605223, 2023). "Altogether, our results indicate that FTO regulates cell cycle profile via suppression of p21cip1 and p27kip1 and that its loss triggers an apoptotic event in pancreatic cancer cells." (PMID 36497402, 2022). "In summary, our study revealed reduced levels of m6A methylation in pancreatic cancer caused by the dysregulation of FTO, the key m6A demethylase modulator." (PMID 35422475, 2022). "In a case-control study, the FTO polymorphism rs9939609 was linked to the risk of pancreatic cancer in Japanese population." (PMID 34239358, 2021). "Another possibility is that FTO is just a proxy of as yet unidentified causal variants, and it is those variants that exert their effects on rs9939609 and influence pancreatic cancer risk." (PMID 23835106, 2013). "We therefore investigated the association between FTO rs9939609 and pancreatic cancer risk in a case–control study in Japan." (PMID 23835106, 2013). "FTO is highly expressed in pancreatic cancer and is associated with poor prognosis." (PMID 40448344, 2025). "FTO, also known as the obesity gene or ALKBH9, has been found to be aberrantly expressed in various cancers and associated with the risk of cancer development, such as breast cancer, thyroid cancer, endometrial cancer, pancreatic cancer, and others." (PMID 39331892, 2024). "In addition, we found that FTO(Obesity-associated protein), a demethylase of m6A modification that induces RNA demethylation, is highly expressed in pancreatic cancer." (PMID 37914721, 2023). "Notably, the observation that loss of FTO is sufficient to inhibit tumor growth of pancreatic cancer cells agrees with the reversal of EMT traits observed upon FTO depletion both in vitro and in vivo in tumors from the xenograft model." (PMID 36497402, 2022). "Furthermore, in a Japanese cohort, the FTO gene variant rs9939609 was reported to be associated with pancreatic cancer risk in an obesity-independent mechanism." (PMID 36497402, 2022). "This was a hospital-based case–control study in Japan to investigate whether genetic variations in the FTO gene were associated with pancreatic cancer risk." (PMID 23835106, 2013). "Of the three studies that examined this association, only one case–control study, conducted at the MD Anderson Cancer Center in the United States, reported that the minor A allele of FTO, rs9939609, was associated with an increased risk of pancreatic cancer among overweight subjects." (PMID 23835106, 2013). "In our study, FTO rs9939609 genotypes were associated with pancreatic cancer risk." (PMID 23835106, 2013). "We conducted a hospital-based case–control study in Japan to investigate whether genetic variations in the FTO gene were associated with pancreatic cancer risk." (PMID 23835106, 2013). "Given that the function of the FTO gene is largely unknown, further studies are needed to comprehensively evaluate multiple SNPs in the FTO gene and elucidate the mechanisms by which FTO rs9939609 influences pancreatic cancer risk." (PMID 23835106, 2013). "Interestingly, another study showed that FTO gene mutations might be positively correlated with pancreatic cancer only in overweight people." (PMID 34239358, 2021). "The FTO-mediated upregulation of platelet-derived growth factor C (PDGFC) autocrine signaling through the m6A/YTHDF2 axis drives pancreatic cancer progression." (PMID 40986143, 2025). "Fat mass and obesity-associated protein (FTO) reduces TFPI2 via N6-methyladenosine (m6A) RNA demethylation, promoting pancreatic cancer and enhancing keratinocyte proliferation and angiogenesis during wound healing." (PMID 40361374, 2025).
pancreatic cancer (continued). "Another example of the oncogenic role of FTO was observed in pancreatic cancer, where FTO induced cancer progression via stabilizing the mRNA of platelet-derived growth factor C (PDGFC)." (PMID 38503745, 2024). "In pancreatic cancer cells, although FTO still inhibited the m6A modification of its target tissue factor pathway inhibitor-2 (TFPI2), unlike PD-L1, the mRNA expression of TFPI2 was decreased because less TFPI2 was bound by YTHDF139." (PMID 38438714, 2024). "In the context of cancer, FTO is significantly upregulated in gemcitabine‐resistant pancreatic cancer, with its stability enhanced by USP7‐mediated deubiquitination." (PMID 39377984, 2024). "We used MK-2209 in combination with FTO overexpression plasmid and verified by plate clone and I50 in vitro experiments that FTO can indeed regulate the proliferation and resistance of pancreatic cancer cells through the PI3K/AKT pathway." (PMID 37605223, 2023). "Immunoprecipitation/mass spectrometry, MeRIP-seq, RNA sequencing and RIP assays, RNA stability, luciferase reporter, and RNA pull down assays were employed to examine the mechanism of FTO affecting gemcitabine resistant pancreatic cancer cells." (PMID 37605223, 2023). "Cells with established gemcitabine resistance and tissues from pancreatic cancer patients were used to evaluate FTO expression." (PMID 37605223, 2023). "We also verified that FTO mRNAmRNA levels were increased in pancreatic cancer relative to normal tissues in the TCGA and GTEx databases, and this was validated in 50 PDAC patient tissues from our hospital." (PMID 37605223, 2023). "Our findings indicated that FTO is substantially expressed in gemcitabine-resistant pancreatic cancer tissues." (PMID 37605223, 2023). "In conclusion, we found that gemcitabine resistance in pancreatic cancer can be influenced by FTO that demethylates NEDD4 RNA in a m6A-dependent manner, which then influences the PTEN expression level and thereby affects the PI3K/AKT pathway." (PMID 37605223, 2023). "Recent research has shown that FTO has an oncogenic impact on pancreatic cancer by directly targeting PDGFC (platelet-derived growth factor C) and stabilizing mRNA expression through m6A." (PMID 37605223, 2023). "Our findings showed that FTO plays an important role in gemcitabine sensitivity in pancreatic cancer cells." (PMID 37605223, 2023). "Correlation analysis showed that the expression level of LINC01134 in pancreatic cancer was positively correlated with the abundance of FTO." (PMID 37914721, 2023). "Our study provides a novel proof of concept for the role of FTO as a therapeutic target for pancreatic cancer." (PMID 36497402, 2022). "To study the role of FTO in pancreatic cancer, we first screened a panel of pancreatic cancer cell lines as they differ in their malignancy nature and state of carcinogenesis." (PMID 36497402, 2022). "FTO inhibits the occurrence of pancreatic cancer by reducing the methylation level of PJA2 mRNA and inhibiting Wnt signaling pathway activation." (PMID 35945641, 2022). "The present study demonstrates that FTO is highly overexpressed in pancreatic cancer vs. normal cells." (PMID 36497402, 2022). "FTO can also promote pancreatic cancer progression by reducing the stability of TFPI-2 mRNA mediated by m6A-YTHDF1." (PMID 36358640, 2022). "This study explicitly provides evidence for the overexpression of FTO in pancreatic cancer vs. normal cells." (PMID 36497402, 2022). "Alterations to m6A modification play various roles in cancers, as the methylated target genes can be proto-oncogenes or tumor suppresser genes, as presented with FTO differential expression levels in pancreatic cancer." (PMID 35409166, 2022). "The effects of FTO stimulation on the biological characteristics of pancreatic cancer cells, including proliferation and colony formation, were investigated in vitro and in vivo." (PMID 35422475, 2022).
pancreatic cancer (continued). "The results presented in this manuscript highlight for the first time the reversal of EMT in pancreatic cancer cells following FTO inhibition and, therefore, their responsibility for inhibiting pancreatic cancer progression." (PMID 36497402, 2022). "They further indicated that FTO knockdown led to a compromised proliferation in pancreatic cancer cells, and in terms of its m6A demethylase activity, led to reduced c-Myc mRNA transcript levels by modulating its m6A enrichment." (PMID 35409166, 2022). "In concordance with the existing studies, we found the upregulation of FTO in various pancreatic cancer cells compared to the normal human pancreatic ductal epithelial cells (HPDE)." (PMID 36497402, 2022). "These two studies on FTO’s role in pancreatic cancer cells present a dual role of FTO in pancreatic tumorigenesis that ought to be addressed, as it is reported as a tumor-promotor by one study while its tumor-suppressor role is addressed in another one." (PMID 35409166, 2022). "The high expression of FTO in pancreatic cancer patients is positively correlated with the progression of the disease." (PMID 34381710, 2021). "The role of FTO in pancreatic cancer is not well understood and needs to be clarified in the future." (PMID 34239358, 2021). "Mechanistically, FTO contributes to the proliferation of pancreatic cancer cells by decreasing the m6A of MYC and basic Helix-Loop-Helix transcription factor (bHLH-TF) and then promoting their translation." (PMID 32612834, 2020). "Tang demonstrated that FTO, a primary demethylase in vivo, was overexpressed in pancreatic cancer cells compared with that in normal pancreatic epithelial cells." (PMID 31810483, 2019). "Knockdown of FTO resulted in impaired proliferation and increased apoptosis of pancreatic cancer cells." (PMID 31810483, 2019). "However, in pancreatic cancer, downregulation of miR‐383‐5p by upregulation of FTO promotes cancer progression by upregulating the expression of integrin subunit alpha 3 (ITGA3), a target of miR‐383‐5p." (PMID 40448344, 2025). "Collectively, we hypothesized that m6A eraser FTO played a potential role in regulating gemcitabine chemosensitivity in pancreatic cancer." (PMID 37605223, 2023). "Our data suggested that GATA6-AS1 can inhibit PDAC cell proliferation, invasion, migration, EMT process and metastasis under hypoxia, and disrupting the GATA6-AS1/FTO/SNAI1 axis might be a viable therapeutic approach for refractory hypoxic pancreatic cancers." (PMID 38057853, 2023). "However, FTO exerted a tumor-suppressing effect in kidney cancer, pancreatic cancer, thyroid cancer, and cholangiocarcinoma." (PMID 35945641, 2022). "Interestingly, we found that all pancreatic cancer cells (PC) screened express markedly higher FTO mRNA levels than that observed in the “normal” human pancreatic duct epithelial cells (HPDE)." (PMID 36497402, 2022). "Furthermore, our results advocate that FTO is a druggable target, and inhibiting FTO overexpression holds significant potential for pancreatic cancer treatment." (PMID 36497402, 2022). "However, despite its functional importance and prognostic implication in tumorigenesis, the relevance of FTO, an m6A eraser, in pancreatic cancer (PC) remains elusive." (PMID 36497402, 2022). "In the present study, through a series of biochemical and molecular analyses, we provide evidence demonstrating the essential role of FTO in the development of highly aggressive attributes of pancreatic cancer and, more significantly, in the maintenance of stemness of pancreatic CSCs." (PMID 36497402, 2022).